TNFSF14 (TNF superfamily member 14)
Description:
Cytokine that binds to TNFRSF3/LTB and TNFRSF14/HVEM and plays major roles in immune system regulation. Upon binding to TNFRSF14/HVEM, delivers costimulatory signals to T cells, leading to T cell proliferation and IFNG production. Binds to the decoy receptor TNFRSF6B thereby disrupts the activation signal initiated by TNFSF14, resulting in reduced T-cell activation.
Synonyms: HVEM-L; CD258; HVEML; LIGHT; LTg
Tractability: Antibody: a drug acting on it is in phase 2 or 3 trials; its Gene Ontology location is reachable by antibodies, with high confidence; UniProt places it where antibodies can reach, with medium confidence; UniProt predicts a signal peptide or a membrane-spanning region. Other modalities: a drug acting on it is in phase 2 or 3 trials.
Target class: Secreted protein
Gene: Protein-coding gene on chromosome 19 (6,658,085 to 6,670,621, reverse strand). Ensembl gene ENSG00000125735.
Subcellular location: Cell membrane (Tumor necrosis factor ligand superfamily member 14, membrane form); Secreted (Tumor necrosis factor ligand superfamily member 14, soluble form); Cytoplasm (Isoform 2)
Subcellular location (Human Protein Atlas): Vesicles; Predicted to be secreted
Pathways (Reactome):
Immune System: TNF receptor superfamily (TNFSF) members mediating non-canonical NF-kB pathway; TNFR2 non-canonical NF-kB pathway; TNFs bind their physiological receptors
Gene Ontology:
Molecular function: cysteine-type endopeptidase inhibitor activity involved in apoptotic process; protein binding; signaling receptor binding; cytokine activity; tumor necrosis factor receptor binding
Biological process: cellular response to mechanical stimulus; positive regulation of non-canonical NF-kappaB signal transduction; T cell costimulation; apoptotic process; cell surface receptor signaling pathway; negative regulation of apoptotic process; negative regulation of inflammatory response; positive regulation of canonical NF-kappaB signal transduction; positive regulation of extrinsic apoptotic signaling pathway; regulation of type II interferon production; signal transduction; T cell activation; T cell homeostasis; T cell proliferation; cell communication; immune response; signaling
Cellular component: decoy receptor complex; plasma membrane; tumor necrosis factor receptor superfamily complex; membrane; cytoplasm; extracellular region
Genetic constraint (gnomAD): Loss-of-function variants: 14 observed, 23.84 expected, observed/expected ratio (o/e) 0.59, 90% interval 0.39 to 0.92. The upper end of that interval is the gene's LOEUF score, 0.92, which puts it in group 3 of 6, group 1 being the genes least tolerant of losing a copy. Missense variants: 255 observed, 294.98 expected, observed/expected ratio (o/e) 0.86, 90% interval 0.78 to 0.96. Synonymous variants: 117 observed, 127.99 expected, observed/expected ratio (o/e) 0.91, 90% interval 0.79 to 1.07.
Homologues: Orthologues: chimpanzee TNFSF14 (98% identical), macaque TNFSF14 (94% identical), rabbit TNFSF14 (85% identical), dog TNFSF14 (82% identical), guinea pig TNFSF14 (81% identical), pig TNFSF14 (80% identical), rat Tnfsf14 (78% identical), mouse Tnfsf14 (77% identical), tropical clawed frog tnfsf14 (30% identical), zebrafish tnfsf14 (24% identical). Paralogues in human: TNFSF15 (25% identical), FASLG (23% identical), LTB (23% identical), TNF (20% identical), TNFSF10 (20% identical), CD40LG (19% identical), LTA (19% identical), TNFSF11 (18% identical).
Diseases named in the same sentence as TNFSF14 in open-access papers:
TNFSF14 is named in the same sentence as 205 diseases in open-access papers, as found by Europe PMC text mining. Sharing a sentence is not in itself a finding about the gene and the disease. The quoted sentences say what the papers report.
COVID-19 (27 papers, 2020 to 2026). A disease caused by infection with severe acute respiratory syndrome coronavirus 2. "Patients with COVID-19–associated ARDS have elevated free serum levels of the cytokine lymphotoxin-like inducible protein that competes with glycoprotein D for herpesvirus entry on T cells (LIGHT; also known as TNFSF14)." (PMID 34871182, 2022). "TNFSF14 is an important modulator of critical innate and adaptive immune responses and plays an important role in the COVID-19 pathogenesis." (PMID 37735363, 2023). "A third module (c) revolves around TNF and includes IL1A, IL1B, TNFSF14, TNFAIP3, and CSF2 that likely mediates the inflammatory response associated with COVID-19 progression." (PMID 35085325, 2022). "The novel therapeutic target cytokine LIGHT (TNFSF14) was recently shown to play a major role in COVID-19-induced acute respiratory distress syndrome (ARDS)." (PMID 35203474, 2022). "Of note, levels of TNFSF14 (also known as LIGHT) were higher in COVID-19 patients with severe compared with those with moderate disease, consistent with a recent report." (PMID 33232303, 2021). "TNFSF14 was recently reported to be upregulated in COVID-19 patients together with OSM and S100A126, which both showed higher levels in our analysis." (PMID 33239683, 2020). "Notably, the expression of genes encoding both TNFSF14 and OSM were down-regulated in the PBMCs from COVID-19 patients with severe disease in the analysis of CITE-seq data, which suggests a tissue origin for these cytokines." (PMID 32788292, 2020). "Finally, these results highlight molecules such as EN-RAGE or TNFSF14, and their receptors, which could represent attractive therapeutic targets against COVID-19." (PMID 32788292, 2020). "The levels of apoptosis mediator proteins, such as caspase-8 and TNF superfamily member 14 (TNFSF14), were significantly higher in COVID-19 patients than those in healthy control." (PMID 33714258, 2021). "scRNA-seq results of COVID-19 find that changes of host factors including EN-RAGE, TNFSF14, oncostatin M, ANXA1, FPR1, and S100A8/9 are correlated with disease severity, revealing the possible pathogenesis of severe COVID-19 and potential host therapeutic targets." (PMID 35495713, 2022). "Also of interest is that sustained upregulations of HGF, TNFSF14 and CASP-8 have been observed in studies on COVID-19 patients as an indicator for severe disease." (PMID 34948231, 2021). "Of note, the TNFSF14 is distinctively enhanced in the plasma of COVID-19–infected individuals but not in cases of other related pulmonary infections such as influenza (flu) virus and respiratory syncytial virus (RSV)." (PMID 32788292, 2020).
asthma (24 papers, 2014 to 2025). "LIGHT (lymphotoxin-related inducible ligand that competes for glycoprotein D binding to herpes virus entry mediator on T cells, also known as TNFSF14) has been identified as a pathogenic threat in various inflammatory diseases such as asthma." (PMID 38173723, 2023). "The cytokine TNFSF14 was demonstrated to be an important factor in the development of lung tissue remodeling in the murine model, which is associated with asthma, IPF, and systemic sclerosis." (PMID 34368225, 2021). "MiR-326 targets TNFSF14 and exacerbates the airway remodeling in asthma by inducing ASM cell proliferation and ECM deposition." (PMID 35172671, 2022). "Taken together, these findings strongly suggest that TNFRSF14:TNFSF14 interactions can influence the pathology of asthma models by mechanisms in addition to effects on the production of Ag-specific IgE." (PMID 27982078, 2016). "Because TH2 cells can enhance the production of Ag-specific IgE antibodies in response to sensitization with Ag, such effects of TNFSF14 on TH2 cells could contribute to the development of IgE-dependent features of asthma models." (PMID 27982078, 2016). "In addition to the well described TNF/IL-1 ligands, the superfamily member LIGHT (TNFSF14) is a T cell coactivator that mediates chronic airway inflammation and is associated with asthma disease severity." (PMID 24982697, 2014). "Moreover, in WT mice, blocking TNFRSF14:TNFSF14 interactions with an antibody administered weeks after Ag sensitization can diminish multiple features of asthma pathology, including blood levels of Ag-specific IgE, airway inflammation and AHR, and airway remodelling." (PMID 27982078, 2016). "Recent data have implicated another member of the TNF superfamily, the ligand TNFSF14 (also known as LIGHT (lymphotoxin-related inducible ligand that competes for glycoprotein D binding to herpesvirus entry mediator on T cells)), in asthma pathology." (PMID 27982078, 2016). "Here the authors show that TNFSF14 acting on its receptor TNFRSF14 on mast cells enhances their IgE-dependent activation and that interference with this pathway attenuates features of asthma pathology in mice." (PMID 27982078, 2016). "LIGHT (TNFSF14) is a cytokine that we previously suggested may be central to lung diseases exhibiting fibrosis and inflammation, including asthma and interstitial lung disease." (PMID 40972652, 2025). "The TNF superfamily member TNFSF14 (LIGHT), via interactions with the receptor TNFRSF14 (HVEM), can support TH2 cell generation and longevity and promote airway remodelling in mouse models of asthma, but the mechanisms by which TNFSF14 functions in this setting are incompletely understood." (PMID 27982078, 2016).
colitis (18 papers, 2011 to 2025). Inflammation of the colon. "Previous work has demonstrated that a member of the TNF superfamily, TNFSF14 (LIGHT), which is pro-inflammatory in several contexts, surprisingly plays an important role in protection from inflammation in mouse models of colitis, with LIGHT deficient mice having more severe disease pathogenesis." (PMID 30524422, 2018). "Mice with Tnfsf14 deficiency were found to undergo more serious colitis and have lower survival rates than wild-type mice, suggesting that LIGHT may mediate innate immune activities and the resilience of gut inflammation by transmitting signals through lymphotoxin β receptors in the colon." (PMID 36145301, 2022). "In a Tnfsf14(-/-) mouse model, it was observed that these mice developed more severe colitis compared to control mice, indicating the protective role of TNFRSF14 in colitis." (PMID 39144148, 2024). "We previously reported that the TNF-superfamily molecule TNFSF14 (LIGHT) is required for preventing severe disease in mouse models of colitis." (PMID 33568785, 2021). "A significant up-regulation of genes encoding the following cytokines and their receptors—Il13, Il16, Il27, Il2rb, Il2rg, Il6r Il10ra, Faslg, Ltb, Osm, Spp1, Tnf, Tnfsf14—was noted in animals with colitis (CβG−)." (PMID 31590413, 2019). "Additionally, the levels of the transcripts encoding arginase 1 (Arg1) and tumor necrosis factor super family 14 (Tnfsf14; Light), which are anti-inflammatory during colitis, were also significantly decreased in infected Tln1Δmye colon tissues." (PMID 38102166, 2023). "Furthermore, the important role of soluble form TNFSF14 is confirmed in the pathogenesis of liver inflammation and DSS-induced colitis." (PMID 33231567, 2020). "Over expression of TNF superfamily member 14 (TNFSF14, or LIGHT [homologous to lymphotoxins, exhibits inducible expression, and competes with HSV glycoprotein D for HVEM, a receptor expressed by T cells]) in transgenic mice leads to colitis." (PMID 30524422, 2018). "Our previous work demonstrated that a member of the TNF superfamily, TNFSF14 or LIGHT (homologous to lymphotoxins, exhibits inducible expression, and competes with HSV glycoprotein D for HVEM, a receptor expressed by T cells), plays a significant role in two mouse models of colitis." (PMID 33568785, 2021). "Although it was confirmed that platelets in the diabetic patients or activated T cells in acute DSS-induced colitis were the important cellular source of plasma levels of TNFSF14, the possibility could not be dismissed that other cell types might be capable of shedding TNFSF14." (PMID 33231567, 2020).
glioma (17 papers, 2019 to 2025). A benign or malignant brain and spinal cord tumor that arises from glial cells (astrocytes, oligodendrocytes, ependymal cells). "The expression of ICOS, TNFSF14, and ULBP1 was assessed by immunohistochemistry in patients with glioma, confirming that TNFSF14 was associated with the clinical outcome of patients with glioma." (PMID 31451090, 2019). "CD44 and TNFSF14 were significantly overexpressed in GBM compared to WHO Grade 3 glioma (confirmed by TCGA, CGGA, and Rembrandt), as well as LGG and normal brain tissue (confirmed by Rembrandt and qPCR analysis)." (PMID 39977830, 2025). "Cluster of differentiation 44 (CD44) and tumor necrosis factor superfamily member 14 (TNFSF14) were found to be significantly overexpressed in GBM compared to lower-grade glioma (LGG) and normal brain tissue." (PMID 39977830, 2025). "TNFSF14/LIGHT was expressed higher in higher-WHO-grade gliomas and mesenchymal subtypes, and it was sensitive as a prognostic marker in GBM and low-grade glioma (LGG)." (PMID 36341396, 2022). "To further investigate the clinical significance of TNFSF14 in glioma, we analyzed the expression of TNFSF14 according to grade of glioma." (PMID 32310827, 2020). "In addition TNFSF14 can also influence tumor growth by modulating tumor angiogenesis and microenvironment in gliomas." (PMID 40342824, 2025). "We found that TNFSF14 expression level increased with increasing glioma grade." (PMID 32310827, 2020). "Using WGCNA and LASSO algorithms, we identified four MHC-related genes (TNFSF14, MXRA5, FCGR2B, and TNFRSF9) as prognostic biomarkers for glioma." (PMID 40429753, 2025). "To further explore the role of MHC in gliomas, we used LASSO regression analysis and identified four genes (TNFSF14, MXRA5, FCGR2B, and TNFRSF9) related to the major histocompatibility complex (MHC)." (PMID 40429753, 2025). "ALKBH5 expression showed positive association with ICP receptors such as TNFRSF14, CD40, CD96 and CD200R1, and ICP ligands such as PDCD1LG2, CD70, TNFSF14, ICOSLG and CD274 in glioma tissues." (PMID 35444654, 2022). "In murine glioma, HEV formation was induced by treatment with a vascular targeting peptide delivering LIGHT/TNFSF14 or when using a lymphotoxin β receptor agonist, and was further enhanced by anti-VEGF and ICI therapy." (PMID 34539661, 2021). "Despite recent advances in our understanding of the function of TNFSF14/LIGHT in a variety of cancer types, the clinical and immunological importance of TNFSF14/LIGHT in human gliomas has not been fully explained." (PMID 36341396, 2022). "It has been reported that CD40, TNFSF14, LGALS9, and SIGLEC10 high expression levels are associated with glioma malignancy grade and negative prognosis." (PMID 35187044, 2021). "In addition, overexpression of TNFSF14 can promote the formation of T-cell-rich TLS and effective anti-tumor T cell response, prolonging the survival of glioma cells, indicating that TNFSF14 may be a biomarker for predicting immunotherapy response." (PMID 38720884, 2024). "Therefore, we hypothesized that high ALKBH5 expression altered the immune microenvironment in the glioma tissues by modulating the expression levels of ICP receptors and ligands such as TNFRSF14, CD40, CD96, PDCD1LG2, CD70 and TNFSF14." (PMID 35444654, 2022).
Obesity (14 papers, 2013 to 2026). Accumulation of substantial excess body fat. "Interestingly, Tnfsf14 deficient mice showed increased obesity, hepatosteatosis, insulin resistance, glucose intolerance, and mitochondrial dysfunction respect to wild-type mice on a HFD." (PMID 36917420, 2023). "A higher level of TNFSF14 has been reported in patients with Prader–Willi syndrome, a disease characterised by obesity and bone impairment." (PMID 40684041, 2025). "We have also recently published that ablation of TNFSF14 in vivo promotes high fat diet-induced obesity, glucose intolerance, insulin resistance, hyperinsulinemia, liver steatosis and adipocyte hypertrophy and inflammation." (PMID 34638990, 2021). "It was encouraging to see that other investigators also noted that TNFSF14 reduced HFD-induced obesity and adipocyte hypertrophy which solidifies our findings." (PMID 34638990, 2021). "Obesity is associated to a low-grade inflammation that alters the expression of adiponectin, leptin, IL-6, Monocyte Chemotactic Protein 1 (MCP1), TRAIL, LIGHT/TNFSF14, OPG, and TNFα." (PMID 31130918, 2019). "Importantly, the TNFSF14 peptide 7 reduced high fat diet-induced glucose intolerance, insulin resistance and hyperinsulinemia in a mouse model of obesity." (PMID 34638990, 2021). "Importantly, our team has recently shown that the TNF superfamily (TNFSF) member protein, TNFSF14, has been reported to protect against high fat diet induced obesity and pre-diabetes." (PMID 34638990, 2021). "TNFSF14/HVEM (herpesvirus entry mediator) are involved in obesity-induced inflammation by recruiting and enhancing macrophage lineage in adipose tissue, thus subsequently responsible for the release of several pro-inflammatory cytokines including TNFα, IL6 and MCP-145." (PMID 30242179, 2018). "Interestingly, treatment of human primary adipocytes with TNFSF14 resulted in a potent inhibition of adipocyte differentiation and accumulation, suggesting that TNFSF14 may protect against obesity." (PMID 34638990, 2021). "Therefore, we conclude that TNFSF14-derived molecules may improve glucose homeostasis and lipid metabolism and may therefore open a completely novel therapeutic pathway for treating obesity and T2D." (PMID 34638990, 2021). "We conclude that TNFSF14-derived molecules positively regulate glucose homeostasis and lipid metabolism and may therefore open a completely novel therapeutic pathway for treating obesity and T2D." (PMID 34638990, 2021). "The proteins that were increased in diabetes, including OSM, IL-8, IL-18R, TNFSF14, TNF and IL-6, play roles in obesity, insulin resistance, beta cell function and vascular diabetes complications." (PMID 41175199, 2026). "Another soluble factor of interest in obesity and T2D is the Tumor Necrosis Factor (TNF) superfamily member, TNFSF14." (PMID 34638990, 2021).
autoimmune disease (13 papers, 2013 to 2025). A disorder resulting from loss of function or tissue destruction of an organ or multiple organs, arising from humoral or cellular immune responses of the individual to their own tissue constituents. "As most of the co-stimulatory members of the TNF/TNFR superfamily, TNFSF14 has been studied for its impact on autoimmune disease and transplant rejection." (PMID 23844029, 2013).
pulmonary fibrosis (13 papers, 2017 to 2026). Chronic progressive interstitial lung disorder characterized by the replacement of the lung tissue by connective tissue, leading to progressive dyspnea, respiratory failure, or right heart failure. "In addition, we found that carriers of the TNFSF4rs7526628T/T genotype showed decreased serum levels of TNFSF14, a protein that has been shown to be involved in the development of pro-inflammatory responses but also in lung tissue remodeling and lung fibrosis." (PMID 33374839, 2020).